TRPM8 (transient receptor potential cation channel subfamily M member 8)
Diseases named in the same sentence as TRPM8 in open-access papers (continued):
Sharing a sentence is not in itself a finding about the gene and the disease.
cancer (continued). "In this context, several antagonists against TRPM8, such as BCTC, sesamin, and cannabigerol, were tested in various cancers, and proved to have an antitumoral effect." (PMID 35361751, 2022). "Genetic alterations were correlated with transcriptome dysregulation of TRP genes, and we found that TRPM2, TRPM8, and TPRA1 showed extent dysregulation in cancer." (PMID 35614079, 2022). "Another TRPM8 agonist, WS12, when encapsulated into lipid nanocapsules, impaired cancer cell migration ability." (PMID 36844925, 2022). "Contrarily, six ion channels are overexpressed in cancers and promote the activity of Wnt pathway (TRPC5, TRPV4, TRPM4, TRPM8, P2RX7, and ASIC1a)." (PMID 33117152, 2020). "In this regard, alterations in the expression of TRP Melastatin 2 (TRPM2), TRPM4, TRPM8, TRP Vanilloid 1 (TRPV1) and TRPV6 have been observed in PCa cells, some of them related to cancer cell survival." (PMID 32344908, 2020). "In PCa cells, TRPM8 enhances HIF-1α, a subunit of the transcription factor HIF-1, which promotes hypoxic growth capacity, angiogenesis, and drug resistance in cancer cells." (PMID 31801263, 2019). "Oxidation of thiol redox system and cysteine groups in cancer cells have the main role in the activation of thiol group containing TRP channels such as TRPA1, TRPM8 and TRPV1." (PMID 30858386, 2019). "Studies have demonstrated that some other TRP channels are highly expressed in cancer cells, and the amount of protein expresssion varies with the progression from normal to tumorigenic to metastatic cells, such as TRPM1, TRPM8, and TRPV6." (PMID 27023518, 2016). "Given TRPM8 is overexpressed in oral squamous cell carcinoma (SCC), its antagonist RQ-00203078 was used to prove a reduction in the invasion and migration capability of SCC cancer cells, via a reduction on calcium influx." (PMID 39940997, 2025). "Many papers suggest that TRPM8, TRPV6, or TRPA1 could be either markers of PDAC or specific targets for cancer therapies based on their localization in the cell membrane, making them easily druggable." (PMID 38543130, 2024). "These functions appear to be unique from their roles in normal noncancerous cells, where activation of TRPM8 appears to have promising antitumor effects in cancer cells." (PMID 37445615, 2023). "TRPM8 expression increases in the three types of cancer in the “not metastatic” condition compared to healthy samples." (PMID 35565390, 2022). "In particular, residues E207 and Y240 in the sequence of TRPM8 and Y32 in that of Rap1A are critical for the interaction between the two proteins not only in PC3 cells but also in cervical (HeLa) and breast (MCF-7) cancer cells." (PMID 35565390, 2022). "Moreover, we also revealed several tissue or group-enriched genes (such as TRPM8, TRPA1, and TRPM3) in cancer." (PMID 35614079, 2022). "Though no distinct isoform for this protein is known so far, some alternative translation of this protein has already been reported and may take place in some diseases like cancer, as it was shown previously for the other TRP channel, TRPM8." (PMID 36613866, 2022). "Last but not least, TRPM8 seems to play an important role in the different steps of cancer progression, including proliferation, apoptosis, and metastasis." (PMID 34445208, 2021). "TRPM8 immunohistochemistry specifically marks the epithelial compartment of the prostate tissue, with cancer cells (HMWCKs negative lumens) more intensely stained than the adjacent normal epithelium (HMWCKs positive lumens)." (PMID 33288740, 2020). "Moreover, cannabigerol (CBG), a non-psychotropic cannabis-derived cannabinoid, used at 10 μM, potently blocks TRPM8 in CRC and protects against cancer development and progression." (PMID 31801263, 2019). "In the same line, expression of non-channel cytoplasmic small TRPM8 isoforms (namely sM8) is conserved in cancer cells." (PMID 27074561, 2016).
cancer (continued). "In addition to SOCE channels, several TRP channels contribute to the migration of cancer cells, including TRP channels TRPC1, TRPM7, TRPM8, TRPV1, TRPV2, and TRPV6." (PMID 26496025, 2015). "Consequently, conventional TRPM8 modulators have not been sanctioned as novel cancer treatments due to the emergence of adverse effects observed in initial trials." (PMID 39062591, 2024). "In addition, though no isoform for this protein is known so far, some alternative translation of this protein has already been reported and may take place in some diseases like cancer, as it was shown previously for the other TRP channel, TRPM8." (PMID 36613866, 2022). "Even though menthol activates TRPM8, the magnitudes of these transients did not correlate with the TRPM8 expression levels in certain cancer cells indicating a TRPM8-independent signaling pathway." (PMID 30483120, 2018). "Concerning the therapeutic targeting of the channel, at first sight the evolution of TRPM8 expression during carcinogenesis might seem not in full accordance with the anti-cancer effect of the channel activation." (PMID 27409624, 2016). "However, the androgen-TRPM8 colocalization remained static in the malignant tissues in comparison to controls, indicating that their interactions do not contribute to the cancer progression." (PMID 25980497, 2015). "However, to our knowledge, there are no TRPM8 modulators FDA-approved for cancer treatment." (PMID 37033630, 2023). "In addition to supporting a potential use of TRPM8 in anti-tumor therapy as a dual target to simultaneously counteract metastatic dissemination and angiogenesis, they also shed new light on the possibility of using TRP channels as targets for the development of peptidomimetics in cancer therapy." (PMID 37576340, 2023). "However, our pharmacological blockade and siRNA experiments strongly support the idea that the inhibition of the channel reduces the proliferation of cancer cells without affecting non-tumor cell proliferation, despite the fact that non-tumor cells also express TRPM8." (PMID 23251635, 2012). "Several of our observations point to a context-dependent role of TRPM8, which seems necessary for cell cycle progression and migration of LNCaP and DU145 cancer cells, while it has only small (if any) effects in non-cancer PNT1A cells and has been reported to inhibit migration of PC3 cells." (PMID 23251635, 2012).
tumor (98 papers, 2009 to 2026). "And the expression of TRPM7 and TRPM8 exhibited significant associations with the tumour Ki67 proliferation index, tumour size, and Scarff-Bloom-Richardson (SBR) grade." (PMID 40078961, 2025). "We observed a large number of mutations that are present in the TRPM8 in tumor samples as somatic mutations." (PMID 39150496, 2024). "High levels of TRPM8 were linked to unfavorable prognosis, immune cell infiltration, and the tumor microenvironment, as well as correlating with abnormalities in the transcription levels of genes associated with immunity and DNA repair." (PMID 35847920, 2022). "A positive association between the expression levels of TRPM8 and histological grade or tumor stage was established." (PMID 26512697, 2015). "In these cells, the activity of TRPM8 may be hormone-dependent, as its expression is regulated by estrogen receptor alpha (ERa) and estrogen, and is associated with the status of tumor estrogen receptors." (PMID 40078961, 2025). "Thus the therapeutic potential of TRPM8 is very constrained, but its elevated correlates can suggest a high risk of tumour metastasis." (PMID 40078961, 2025). "Furthermore, increases in TRPM8 gene expression are associated with rises in etoposide sensitivity during tumor progression in other studies." (PMID 38339011, 2024). "Clinical studies revealing the overexpression of TRPM8 in various tumors give rise to the hypothesis that TRPM8 may be implicated in tumorigenesis and tumor progression." (PMID 35361751, 2022). "TRPM8 is strongly associated with tumor physiology and immunity." (PMID 35847920, 2022). "Thus, TRPM8 appears to be involved in pathways associated with tumor physiology and immunity." (PMID 35847920, 2022). "Some recent studies have highlighted the crucial role of two types of TRP channels, TRPM7 and TRPM8, in regulating cell metabolism in certain tumor types." (PMID 40813985, 2025). "The dual regulatory role of TRPM8 on both tumor cells and immune cells provides a foundation for targeted drug selection and delivery strategies." (PMID 40535121, 2025). "TRPM8 overexpression correlated positively with tumor size, stage, and multiplicity in various patient tissues, and that the channel was overexpressed in various liver cancer cell lines compared to healthy cell lines." (PMID 40813985, 2025). "In this section, we discuss recent findings involving TRPM7 and TRPM8 in metabolic reprogramming in different tumor types." (PMID 40813985, 2025). "For instance, both TRPV1 and TRPM8 can exert either tumor-promoting or tumor-inhibiting effects, depending on the stage of the tumor, the composition of the tumor microenvironment, and the specific intracellular signaling milieu." (PMID 40869148, 2025). "As a Ca2+-permeable cation channel, TRPM8 mediates intracellular Ca2+ signaling transduction and interferes with the cell cycle via CamKII, cdc25C, and cdc2, thereby promoting tumor cell proliferation and the development of radioresistance." (PMID 40535121, 2025). "TRPM7 and TRPM8 are highly expressed in human breast ductal adenocarcinoma (hBDA) compared to adjacent non-tumor cells, with their expression levels correlating to specific pathological parameters." (PMID 39633507, 2024). "Nevertheless, icilin was frequently used as a relatively selective TRPM8 agonist in other types of tumor cells." (PMID 38339011, 2024). "TLR3-activation by extracellular vesicle-delivered TRPM8 mRNA triggers aseptic inflammation in the prostate epithelium, promoting tumor suppression by NK cells." (PMID 38316991, 2024). "This study identifies TRPM8 transcripts as androgen-independent driver of sterile inflammation in the prostate gland, promoting anticancer innate immunity in the tumor microenvironment." (PMID 38316991, 2024). "While various TRPM8 blockers have been shown to suppress different stages of PCa cell growth in vitro, TRPM8 demonstrated anti-tumor effects in vivo, limiting tumor growth and metastasis in a mouse transplanted tumor model." (PMID 39633507, 2024).
tumor (continued). "TRPM8 exerts multifaceted effects on the gut, influencing sensory, motor, inflammatory, and tumor-related processes, with a growing body of mechanistic studies providing deeper insights." (PMID 39062591, 2024). "However, the impact of TRPM8 in the development and progression of PCa is subject to complex modulation mechanisms that also underlie the expression of different isoforms with distinct subcellular localization and activity depending on tumor stage and androgen sensitivity." (PMID 37576340, 2023). "TCAF2 in TPCs inhibited the expression and ion channel activity of TRPM8, promoting tumor cell EMT and metastasis via activation of the Wnt5a/STAT3 signaling pathway." (PMID 37635201, 2023). "Channel inhibition with the antagonist AMTB or TRPM8 knockdown decreased the tumor growth induced by g-irradiation by suppressing DDR and promoting radio sensitizing." (PMID 37033630, 2023). "Our study revealed the pro‐metastatic effects of TCAF2 and TRPM8 in TPCs from a new perspective on ion channels, providing a potential target for inhibiting tumor metastasis." (PMID 37635201, 2023). "Further investigation showed that TRPM8 expression was lower in TPCs from primary tumor tissues derived from CRC patients with liver metastasis than that in TPCs from patients without metastasis." (PMID 37635201, 2023). "Pearson's correlation analysis indicated that the expression of TRPM8 was negatively correlated with the expression of TCAF2 in NG2+ TPCs of tumor xenografts." (PMID 37635201, 2023). "Despite a certain level of inter-tumor heterogeneity, TRPM8 immunolocalization shows a well-conserved expression of the channel in human hormone-naïve primary PCa and proximal lymph node metastases." (PMID 35204694, 2022). "In mammals, TRPM8 was first described in sensory neurons connected with cold perception and was subsequently found in many other cell types, including tumor cells." (PMID 35847920, 2022). "Our in vitro and in vivo results shed light on the role of TRPM8 on PCa AR–negative tumor growth and metastasis dissemination." (PMID 35743115, 2022). "In particular, we evaluated the impact of TRPM8 on primary tumor growth and metastatic dissemination, further investigating the molecular mechanisms underlying TRPM8′s effects on PCa progression." (PMID 35743115, 2022). "On the other hand, anti‐ELTD1 and combined therapies were all successful in significantly decreasing TRPM8 positivity staining within the tumour region (anti‐ELTD1: UT *p = 0.0132, bevacizumab **p = 0.0045; combined: UT **p = 0.0095, bevacizumab **p = 0.0034)." (PMID 34910361, 2022). "Transient receptor potential melastatin 8 (TRPM8) modulates tumor biology and sensitivity to treatment." (PMID 35847920, 2022). "TRPM8 mRNA expression detected by real-time qRT-PCR was up-regulated in the tumor xenografts stably expressing WT-TRPM8 or TRPM8-Y1022F." (PMID 35665750, 2022). "ERG+ tumor cells were characterized by expression of ERG and tumor markers PCA3, AMACR, and TRPM8;35–37ERG− tumor cells were marked by the expression of tumor markers PCA3 and TRPM835–37." (PMID 35013146, 2022). "We used a prostate orthotopic xenograft mouse model to show that TRPM8 overexpression dramatically limited tumor growth and metastasis dissemination in vivo." (PMID 35743115, 2022). "According to RNAseq studies, TRPM8 expression declines drastically with tumor progression to the castration-resistant stage of the disease." (PMID 35204694, 2022). "We found a significant difference between mice grafted with PC3 luc and those grafted with PC3–M8 luc in terms of bioluminescent foci, indicating that a strong reduction in tumor cell dissemination was carried out by TRPM8." (PMID 35743115, 2022). "In this work, we clarified the role played by TRPM8 in PCa progression in vivo, mainly focusing on its effects on tumor growth and metastasis dissemination." (PMID 35743115, 2022).
tumor (continued). "In particular, we showed that TRPM8 overexpression decreased the proliferation and clonogenic properties of PCa cells, resulting in dramatically limited tumor growth in orthotopic graft mice." (PMID 35743115, 2022). "TRPM8 expression not only reduced tumor weight and area, but also affected its histological features, helping to maintain well–defined glandular tissue." (PMID 35743115, 2022). "The comparison of the tumor area between PC3 luc and PC3–M8 luc grafts also confirmed the inhibitory role of TRPM8 in PCa growth, showing a reduction in the tumor area of 79.91 ± 3.28% in PC3–M8 luc cl5 and 64.24 ± 3.41% in PC3–M8 luc cl2." (PMID 35743115, 2022). "For instance, high TRPM8 expression was significantly correlated with large tumor size, advanced TNM, and distant metastasis." (PMID 36012311, 2022). "Analogously, tryptophane-derived TRPM8 antagonists inhibit proliferation in the LNCaP cell line as well as in metastatic and resistant tumor cell C4-2B, 22Rv1, and DU-CaP lines." (PMID 36844925, 2022). "Immunofluorescence and histological analyses were further performed to verify TRPM8 expression in our prostate orthotopic tumor model." (PMID 35743115, 2022). "The grade-dependent expression level of TRPM8 in several major tumor types was also evaluated using immunohistochemistry (IHC)." (PMID 35847920, 2022). "It thus appears that TRPM8 overexpression activates these pathways, with TRPM8 stimulating angiogenesis, tumor viability, and growth." (PMID 35847920, 2022). "In the meanwhile, in vitro interfering of the normal function of TRPM8 proves to have minor side effect on immortalized normal cells, making TRPM8 a valuable therapeutic target in tumor treatment." (PMID 35361751, 2022). "We also employed a novel metastatic zebrafish xenotransplantation model to detect the effect of mutant TRPM8-Y1022F on tumor cell migration." (PMID 35665750, 2022). "Mechanistically, our in vitro data revealed that TRPM8 inhibited tumor growth by affecting the cell proliferation and clonogenic properties of PCa cells." (PMID 35743115, 2022). "Our in-silico analysis of large RNAseq and microarray datasets highlights a substantial inter-tumor heterogeneity of TRPM8 mRNA levels in PCa samples with the full length mRNA generally more abundant compared to its shorter isoforms." (PMID 34514058, 2021). "Among the growing list of ion channels expressed in normal and tumor prostate epithelial cells, Transient Receptor Potential Melastatin 8 (TRPM8) stands out as one of the most promising clinical targets for PCa treatment." (PMID 34514058, 2021). "To accurately profile TRPM8 expression in normal and tumor prostate tissue, we have interrogated widely used RNA-seq24–26 and microarray PCa datasets." (PMID 33288740, 2020). "BASF extended its previous patents, and therefore increased the TRPM8 agonist chemotypes useful for application in the pharmaceutical field (tumor treatment, and bladder weakness, among others)." (PMID 31141957, 2019). "Next, we isolated CD8+ T cells from participants and created co-incubation system to assess the role of TRPM8 in the anti-tumor effect of CD8+ T cells on EC109 cells." (PMID 31519770, 2019). "Numerous experimental results link the expression of the TRPM8 channel with cell migration and tumor progression." (PMID 31141957, 2019). "Distinct from the HOTPAM9 kinases and not a part of the network is the Transient Receptor Potential cation channel subfamily member M8, TRPM8, which regulates PC cell migration, and hence suggests a role in tumor metastasis 30,31." (PMID 31273254, 2019). "Recovery of the TRPM8 protein expression on the plasma membrane significantly induced the apoptotic cell death, suggesting that this channel plays a tumor suppressor role in LNCaP cells." (PMID 28039451, 2017). "In healthy individuals, TRPM8 expression preferentially demonstrated plasma membrane and ER pattern, whereas the channel was severely internalized in the tumor tissues." (PMID 28039451, 2017).